MEG8 (maternally expressed 8, small nucleolar RNA host gene)
Diseases named in the same sentence as MEG8 in open-access papers (continued):
Sharing a sentence is not in itself a finding about the gene and the disease.
Wilms tumor (1 paper, 2022). An embryonal neoplasm characterized by the presence of epithelial, mesenchymal, and blastema components. "In Wilms tumor samples, expression of MEG8 has been correlated with histological subtype, lymphatic invasion, and National Wilms Tumor Study (NWTS) stage." (PMID 36114498, 2022). "Taken together, MEG8 regulates pathogenesis of Wilms tumor through miR-23a-3p/CRK axis." (PMID 36114498, 2022). "Similarly, expression of MEG8 has been found to be elevated in Wilms tumor cells, parallel with up-regulation of CRK and down-regulation of miR-23a-3p." (PMID 36114498, 2022).
cancer (15 papers, 2017 to 2024). A tumor composed of atypical neoplastic, often pleomorphic cells that invade other tissues. "In this work, we explored the role of Rian (RNA imprinted and accumulated in nucleus)/MEG8 in these processes to identify the connection between aging, cellular senescence, and cancer in breast tissue." (PMID 39706842, 2024). "Even though multiple studies have demonstrated that MEG8 expression enhances proliferation and migration of cancer cells as well as of vascular endothelial cells, studies with vascular smooth muscle cells showed the opposite." (PMID 39551752, 2024). "Transfection of cancer cells demonstrated MEG8 overexpression and a simultaneous downregulation of the MEG8 target-miR-107." (PMID 37686426, 2023). "Classical isolation of RNA with a subsequent real-time PCR was applied to evaluate the expression level of MEG8 in cancer and adjacent normal tissues." (PMID 37686426, 2023). "The mechanism involving lncRNA MEG8, miR-15a/b-5p, and PSAT1 enriches the understanding of lncRNA MEG8, benefiting the future investigation of lncRNA MEG8 in other cancers." (PMID 33526036, 2021). "Among the cluster, previous researches have shown MEG3 and MEG8 significantly contribute to epigenetic EMT in the malignant progression of cancer." (PMID 34906173, 2021). "Previous studies have shown a suppression of MEG3 gene in various tumors and a downregulation of MEG8 gene, which is essential for stem cell growth and proliferation, thus resulting into a cancer cell." (PMID 30647841, 2018). "Conversely, this effect could be detrimental later in life as a result of aging and cancer, when MEG8 is reduced and lose its tumor suppressor role." (PMID 39706842, 2024). "Conversely, this effect could be detrimental later in life due to aging and cancer, when MEG8 is reduced and loses its tumor-suppressive role." (PMID 39706842, 2024). "MEG8 has been among 10 lncRNAs that have been related with prognosis of this type of cancer." (PMID 36114498, 2022). "Interestingly, overexpression of MEG8 has been shown to repress miRNA-34a in human cancer cells." (PMID 35611612, 2022). "Since Rian/MEG8 expression decrease with age and is high in mice that age prematurely, we wonder if this gene could act as an antagonistically pleiotropic gene during aging: suppressing the development of cancer early in life and driving age-related pathologies such as cancer late in life." (PMID 39706842, 2024). "In humans, the Rian ortholog, MEG8 (along with MEG3), has been shown to be upregulated in many cancers and is thought to regulate many different pathways by acting as a molecular sponge for various miRNAs." (PMID 38155837, 2023). "The crucial role of the axis MEG8/miR-107/CDK6 in proliferation, cell cycle changes, invasion, and migration that stimulate cancer progression was confirmed by various direct methods including flow cytometry and a cell scratch test." (PMID 37686426, 2023). "Furthermore, low MEG8 levels in endothelial cells are known to impair endothelial function, which in turn, in addition to promoting VTE, also plays a role in cancer by amplifying the tumour inflammatory signalling and consequently promoting tumorigenesis." (PMID 38203310, 2023). "In addition, non-coding host genes have recently been found to be involved in cancer onset or progression, for example ZFAS1, GAS5, and MEG8." (PMID 32046192, 2020). "In the case of MEG8 and MEG9 lncRNAs, their functions in cancer remain unknown." (PMID 29435111, 2018). "Concerning MEG8, its pre-chemotherapy expression levels were significantly elevated in OC patients who later developed a VTE event after cancer diagnosis compared to those without the condition (Mann–Whitney U test; p = 0.037)." (PMID 38203310, 2023).
tumor (15 papers, 2009 to 2025). "Interestingly, in line with the bilateral relationship between tumour cells and the haemostatic system, MEG8 was also demonstrated to impact the risk of OC progression regardless of VTE." (PMID 38203310, 2023). "In NSCLC, the lncRNA MEG8 is expressed at higher levels in tumor tissues than in normal adjacent tissues and promotes tumor progression by regulating the miR-15a/b-5p/PSAT1 axis." (PMID 37147729, 2023). "In HCC patients, over-expression of MEG8 has been correlated with the poor prognosis, edmondson Steiner grading, venous infiltration, and the number of tumor nodules." (PMID 36114498, 2022). "Together these data suggest that lncRNA MEG8 contributes to tumor growth of NSCLC via the miR-15a-5p-miR-15b-5p/PSAT1 axis in vivo." (PMID 33526036, 2021). "MEG8 and TNF-α are upregulated in tumor tissues of oe-MEG8 group, while miR-454-3p is downregulated." (PMID 34016788, 2021). "The effect of lncRNA MEG8, miR-15a-5p, and miR-15b-5p on tumor growth was evaluated in nude mice of Balb/c in vivo." (PMID 33526036, 2021). "LncRNA MEG8 contributes to tumor growth of NSCLC via the miR-15a/b-5p/PSAT1 axis in vivo." (PMID 33526036, 2021). "Results showed that MEG8 overexpressing significantly promoted xenograft tumor volume in vivo." (PMID 34016788, 2021). "Altogether, the MEG8/miR‐378d/SOBP competing endogenous RNA (ceRNA) axis could be the potential mechanism in affecting tumor progression and prognosis of OC." (PMID 33742531, 2021). "This is the first study to show aberrant expression of MEG8, NAV2-AS2, STEAP3-AS1, GLIS3-AS1, LINC00158, AC012640.1 in BC and indicates the potential for prediction of tumour recurrence and assessment of recurrence prognosis in BC patients." (PMID 31892978, 2020). "However, when cells lose the expression of MEG8, SOX9 activity and its downstream target BMI1, proliferation is promoted, bypassing senescence and facilitating tumor formation and progression." (PMID 39706842, 2024). "All of this could explain the inverse correlation between MEG8 and SOX9, since when MEG8 is overexpressed it shows a tumor suppressor role that could not be bypassed by the low levels of SOX9." (PMID 39706842, 2024). "In addition, we reported the novel MEG8/miR‐378d/SOBP ceRNA subnetwork first, and speculate that it may act a crucial part in the tumor progression and immune function of OC by regulating the cytokines pathway." (PMID 33742531, 2021). "Therefore, under a comprehensive analysis and previous reports, we establish the MEG8/miR‐378d/SOBP axis and speculate that it may act a crucial role in the tumor progression and immune function of OC by regulating the cytokines pathway." (PMID 33742531, 2021).
cardiovascular disease (1 paper, 2022). "We hypothesized that MEG8 plays an important role in cardiovascular disease via epigenetic regulation of gene expression." (PMID 35039572, 2022). "This suggests a potentially interesting role for MEG8 in cardiovascular disease." (PMID 35039572, 2022).
heart disease (1 paper, 2022). "MEG8 expression was upregulated threefold in ISHD patients compared to left ventricle tissue from control donors with no history of heart disease." (PMID 35039572, 2022).
infection (1 paper, 2020). The state of being infected such as from the introduction of a foreign agent such as serum, vaccine, antigenic substance or organism. "The short alimentary tract protein MEG-8.2 provides an example, with a broad region of reactivity recognized by all eight sera (row 40, col 44-61) versus a neighboring set of peptides that strongly binds only infection serum 1 (row 42 col 7-11)." (PMID 33763055, 2020).
neurological diseases (1 paper, 2025). "Specifically, we chose the genes TTTY14, TBL1Y, MEG8, MEG9, BCORP1, and RPAS4Y1 for analysis, all of which were found to be unrelated to neurological diseases." (PMID 40600194, 2025).
MEG8 also shares sentences with these, for which no sentence is quoted: atherosclerosis (2 papers); colorectal cancer (2); glioblastoma (2); non-small cell lung carcinoma (2); Obesity (2); pancreatic cancer (2); bladder cancer (1); Burkitt lymphoma (1); glioma (1); ischemic heart disease (1); myocardial infarction (1); osteoarthritis (1); prostate carcinoma (1); thyroid cancer (1); type 1 diabetes (1).